HLA-S (major histocompatibility complex, class I, S (pseudogene))
Synonyms: HLA-17
Gene: Unprocessed pseudogene on chromosome 6 (31,382,074 to 31,382,288, reverse strand). Ensembl gene ENSG00000225851.
Diseases named in the same sentence as HLA-S in open-access papers:
HLA-S is named in the same sentence as 6 diseases in open-access papers, as found by Europe PMC text mining. Sharing a sentence is not in itself a finding about the gene and the disease. The quoted sentences say what the papers report.
cerebrovascular disease (1 paper, 2024). "A recent GWAS of white matter biomarkers in cerebrovascular disease has also revealed alterations in immune cell genes including human leukocyte antigen B (HLA‐B), major histocompatibility complex I (MHC I and HLA‐S), cell‐surface proteins involved in immune system regulation." (PMID 37909242, 2024).
cervical cancer (1 paper, 2024). A primary or metastatic malignant neoplasm involving the cervix. "In particular, the HLAs alleles may play an important role in determining which HPV variant will clear or persist and progress to cervical cancer." (PMID 39681919, 2024).
HLA-S also shares sentences with these, for which no sentence is quoted: hepatocellular carcinoma (1 paper); Hypertension (1); schizophrenia (1); tumours (1).